B3GAT3 (beta-1,3-glucuronyltransferase 3)
Description:
Glycosaminoglycans biosynthesis. Involved in forming the linkage tetrasaccharide present in heparan sulfate and chondroitin sulfate. Transfers a glucuronic acid moiety from the uridine diphosphate-glucuronic acid (UDP-GlcUA) to the common linkage region trisaccharide Gal-beta-1,3-Gal-beta-1,4-Xyl covalently bound to a Ser residue at the glycosaminylglycan attachment site of proteoglycans. Can also play a role in the biosynthesis of l2/HNK-1 carbohydrate epitope on glycoproteins. Shows strict specificity for Gal-beta-1,3-Gal-beta-1,4-Xyl, exhibiting negligible incorporation into other galactoside substrates including Galbeta1-3Gal beta1-O-benzyl, Galbeta1-4GlcNAc and Galbeta1-4Glc. Stimulates 2-phosphoxylose phosphatase activity of PXYLP1 in presence of uridine diphosphate-glucuronic acid (UDP-GlcUA) during completion of linkage region formation.
Synonyms: GlcAT-I; GlcUAT-I; GLCATI; JDSCD
Tractability: Small molecule: a structure with a bound ligand is known; it has a high-quality binding pocket. Antibody: UniProt predicts a signal peptide or a membrane-spanning region. PROTAC: ubiquitination databases record sites on it; its protein half-life has been measured.
Target class: Enzyme; Transferase
Gene: Protein-coding gene on chromosome 11 (62,615,296 to 62,622,154, reverse strand). Ensembl gene ENSG00000149541.
Subcellular location: Golgi apparatus membrane; Golgi apparatus, cis-Golgi network
Pathways (Reactome):
Disease: Defective B3GAT3 causes JDSSDHD
Metabolism: Glycosaminoglycan-protein linkage region biosynthesis
Gene Ontology:
Molecular function: galactosylgalactosylxylosylprotein 3-beta-glucuronosyltransferase activity; glucuronosyltransferase activity; protein binding; protein phosphatase activator activity
Biological process: chondroitin sulfate proteoglycan biosynthetic process; dermatan sulfate proteoglycan biosynthetic process; glycosaminoglycan biosynthetic process; heparan sulfate proteoglycan biosynthetic process; positive regulation of catalytic activity; positive regulation of intracellular protein transport
Cellular component: cis-Golgi network; extracellular exosome; Golgi apparatus; membrane; Golgi membrane
Genetic constraint (gnomAD): Loss-of-function variants: 19 observed, 33.81 expected, observed/expected ratio (o/e) 0.56, 90% interval 0.39 to 0.82. The upper end of that interval is the gene's LOEUF score, 0.82, which puts it in group 3 of 6, group 1 being the genes least tolerant of losing a copy. Missense variants: 344 observed, 450.62 expected, observed/expected ratio (o/e) 0.76, 90% interval 0.7 to 0.83. Synonymous variants: 167 observed, 199.88 expected, observed/expected ratio (o/e) 0.84, 90% interval 0.74 to 0.95.
Homologues: Orthologues: dog B3GAT3 (96% identical), rabbit B3GAT3 (96% identical), mouse B3gat3 (96% identical), pig B3GAT3 (96% identical), macaque B3GAT3 (93% identical), guinea pig B3GAT3 (92% identical), chimpanzee B3GAT3 (90% identical), zebrafish b3gat3 (59% identical), tropical clawed frog b3gat3 (57% identical), Drosophila melanogaster GlcAT-I (41% identical). Paralogues in human: B3GAT1 (48% identical), B3GAT2 (43% identical).
Diseases named in the same sentence as B3GAT3 in open-access papers:
B3GAT3 is named in the same sentence as 31 diseases in open-access papers, as found by Europe PMC text mining. Sharing a sentence is not in itself a finding about the gene and the disease. The quoted sentences say what the papers report.
liver cancer (5 papers, 2020 to 2022). An epithelial or non-epithelial malignant neoplasm that arises from the liver. "High expression of B3GAT3 has been reported to be associated with poor prognosis in liver cancer." (PMID 35707353, 2022). "Moreover, B3GAT3 has been shown to be highly expressed in liver cancer tissues and was associated with poor prognosis, which is consistent with our present study." (PMID 35774357, 2022). "Furthermore, it was found that the high expression of B3GAT3 is disadvantageous to the prognosis of human liver cancer and has independent prognostic value in patients with different pathological features of liver cancer." (PMID 33281878, 2020). "B3GAT3 is highly expressed in liver cancer cells and considered a potential prognostic biomarker." (PMID 33194661, 2020). "Beta-1, 3-glucuronyltransferase 3 (B3GAT3) promotes the proliferation, metastasis and epithelial mesenchymal transition (EMT) process of the human HepG2 liver cancer cell line." (PMID 34557495, 2021).
hepatocellular carcinoma (3 papers, 2020 to 2025). A malignant tumor that arises from hepatocytes. "B3GAT3 catalyzes the final step in the assembly of the common tetrasaccharide linker region of proteoglycans, and its elevated expression in osteosarcoma and hepatocellular carcinoma has been associated with poor prognosis." (PMID 40963867, 2025). "Studies have shown that compared with normal tissues, B3GAT3 is upregulated in human hepatocellular carcinoma, and the knockout of the B3GAT3 gene can inhibit cell proliferation, migration and invasion and reverse the process of epithelial mesenchymal transformation." (PMID 33281878, 2020).
colorectal cancer (2 papers, 2021 to 2022). A primary or metastatic malignant neoplasm that affects the colon or rectum. "The abnormal expression of B3GAT3 accelerated the glycolytic pathway and promoted the proliferation of colorectal cancer cells, thereby affecting the prognosis of patients." (PMID 36605944, 2022).
congenital heart defects (2 papers, 2022 to 2023). "To date, 12 variants in the B3GAT3 gene have been described in 29 patients from 15 families with mild to severe phenotypes, but only half of them presented with heart defects." (PMID 35151321, 2022). "We diagnosed a patient with congenital heart defects at an early age with a B3GAT3-related disorder instead of Marfan syndrome and expanded the spectrum of B3GAT3-related disorders." (PMID 35151321, 2022). "B3GAT3 (OMIM * 606374) is linked to multiple joint dislocations, short stature, and craniofacial dysmorphism, with or without congenital heart defects (OMIM # 245600)." (PMID 36833424, 2023).
Larsen-like syndrome (2 papers, 2015 to 2023). "A mutation (p.Arg277Gln) in the B3GAT3 gene encoding GlcAT-I has been shown to cause Larsen-like syndrome." (PMID 26582078, 2015). "Beta-1,3-glucuronyltransferase 3 (B3GAT3) deficiency [OMIM:245600], also known as Larsen-like syndrome, is a rare AR and idiopathic CDG with a mutation in the B3GAT3 gene on chromosome 11q12.3." (PMID 37239976, 2023).
linkeropathies (2 papers, 2019 to 2023). "To date, five genes, encoding various glycosyltransferases, have been linked to linkeropathies; besides the XYLT2 gene, there are the genes XYLT1 (OMIM * 608124), B4GALT7 (OMIM * 604327), B3GAT3 (OMIM * 606374), and B3GALT6 (MIM:* 615291)." (PMID 36833424, 2023).
cervical cancer (1 paper, 2022). A primary or metastatic malignant neoplasm involving the cervix. "Compared with normal cervix tissues, the expressions of several glycosyltransferases in cervical cancer tissues were upregulated, including GALNT2, POGLUT1, EXT1, B3GAT3, B4GALNT1 and UGT8 (GSE9750)." (PMID 36110252, 2022).
myeloma (1 paper, 2013). "Enzymes relevant for the initiation of GAG formation and heparan sulfate chain elongation, beta-1,3-glucuronyltransferase 3 (B3GAT3), multiple exostosin-like 2 (EXTL2) and EXT2 heparan sulfate copolymerase (EXT2), display enhanced expression in myeloma cells." (PMID 24386263, 2013).
ovarian carcinoma (1 paper, 2020). A malignant neoplasm originating from the surface ovarian epithelium. "We further analyzed the differential expression of B3GAT3, COL5A1, FAM162A, IDUA, and PPP2R1A in ovarian cancer SKOV-3 and A2780 cells and HOSEpiC human ovarian epithelial cells." (PMID 33281878, 2020). "The RT-qPCR results showed that compared with human ovarian epithelial cells, the expression of B3GAT3, COL5A1, FAM162A, IDUA, and PPP2R1A in ovarian cancer cells was significantly downregulated." (PMID 33281878, 2020).
viral infection (1 paper, 2025). "Therefore, although both SLC35B2 and B3GAT3 are involved in HS synthesis, we chose to use B3GAT3 KO cells in our analysis to more specifically evaluate the role of HS in viral infection." (PMID 40548749, 2025).
tumor (8 papers, 2020 to 2025). "Five GRGs (ABCB6, ANKZF1, B3GAT3, KIF20A and STC2) were dysregulated in tumor samples and were independently associated with the prognosis of HCC." (PMID 35123420, 2022). "Since PG could affect the cell cycle and was related to tumor cell invasion and metastasis, the potential role of B3GAT3 in tumor development, progression and prognosis was explored." (PMID 35123420, 2022). "Therefore, inhibiting the expression of B3GAT3 could block the glycolysis pathway of tumor cells, which could effectively decrease the proliferation of tumor cells and even kill tumor cells." (PMID 33391344, 2020). "Glycosyltransferases—including B3GAT3, B3GNT4, and B4GALT2—play distinct yet interconnected roles in glycan biosynthesis, which can influence tumor biology." (PMID 40963867, 2025). "The expression levels of B3GAT3, XYLT1, XYLT2, B4GALT7, and B3GALT6 were significantly upregulated in OS tissues compared to those in non-tumor tissues, according to the analysis of the bulk RNA-seq dataset (PRJNA539828)." (PMID 38690160, 2024). "The violin plot based on TCGA data displayed remarkably different expression levels of ALDH3A2, B3GAT3, and CPT2 in tumor group compared with that of the normal group." (PMID 33194661, 2020). "Nonetheless, several genes significantly increase in tumors and impact patient survival (XYLT2, B3GAT3, EXT2) while HS3ST1 is decreased in tumor." (PMID 33585200, 2020). "The B3GAT3 and CENPA were all significantly upregulated in the tumor tissues." (PMID 33391344, 2020). "However, according to our results, B3GAT3 is expressed at low levels in OC cell lines, and the Coef value of B3GAT3 is −0.136; thus, it is a protective factor that may be related to cancer species and is worthy of further study, This phenomenon may be related to the type of tumor." (PMID 33281878, 2020).
infection (3 papers, 2020 to 2023). The state of being infected such as from the introduction of a foreign agent such as serum, vaccine, antigenic substance or organism. "Enzymatic removal of cell surface HS by heparinase treatment and genetic ablation of HS biosynthesis genes, SLC35B2, exostosin-1, N-deacetylase/N-sulfotransferase I and beta-1,3-glucuronyltransferase 3, significantly reduced infection with multiple genetically distinct PRV species." (PMID 37143369, 2023). "Complementation of B3GAT3−/− cells with B3GAT3 partially restored infection." (PMID 32999033, 2020). "Indeed, studies demonstrated that other molecules, such as SLC35B2 and B3GAT3, are related to the successful entry of EV-A71, as their knockout but not hSCARB-2 decreased EV-A71 infection." (PMID 36992493, 2023).
cancer (2 papers, 2020 to 2022). A tumor composed of atypical neoplastic, often pleomorphic cells that invade other tissues. "Similar expression of POMGNT1 and B3GAT3 was observed in normal versus cancer tissues by immunohistochemical staining." (PMID 35356430, 2022).
skeletal dysplasia (2 papers, 2019). Any Mendelian diseases that affects growth and development of the skeleton. "In summary, our findings expand the B3GAT3 allelic repertoire, corroborate the emergent genotype-phenotype correlations, and confirm the extended phenotypic range of B3GAT3 mutations overlapping skeletal dysplasia and soft HCTDs including EDS." (PMID 31438591, 2019). "Furthermore, we provided a comprehensive overview of the phenotypic features of B3GAT3-related disorders and of all the LKs, thus offering future nosologic perspectives for either EDS or skeletal dysplasias." (PMID 31438591, 2019).
B3GAT3 also shares sentences with these, for which no sentence is quoted: craniosynostosis (2 papers); developmental delay (2); 22q11.2 deletion syndrome (1); atrial septal defect (1); Baratela–Scott syndrome (1); cardiovascular disease (1); colon adenocarcinoma (1); cutis laxa (1); Marfan syndrome (1); mitral valve prolapse (1); osteosarcoma (1); Platyspondyly (1); pseudodiastrophic dysplasia (1); pulmonary stenosis (1); rectum adenocarcinoma (1); retinal detachment (1); Skeletal muscle atrophy (1).